TGFBI (transforming growth factor beta induced)
Diseases named in the same sentence as TGFBI in open-access papers (continued):
Sharing a sentence is not in itself a finding about the gene and the disease.
corneal dystrophies (continued). "That makes both techniques useful for establishing the phenotype features of each TGFBI corneal dystrophy and monitoring the progression of the disease." (PMID 21921985, 2011). "Two years later, TGFBI protein (TGFBIp) was found expressed in the cornea and its chromosome locus found to be involved in corneal dystrophy." (PMID 22194646, 2011). "Identification of novel mutations, the presence of phenotypic variability, and the genetic heterogeneity seen in our cases stress the need for mandatory screening of TGFBI for precise diagnosis and classification of corneal dystrophies." (PMID 20680100, 2010). "We investigated the role of TGFBI/BIGH3 in Groenouw corneal dystrophies by generating transgenic mice overexpressing TGFBI/BIGH3 containing the R555W mutation." (PMID 18568131, 2008). "Molecular genetic analysis of TGFBI can offer a rapid, accurate diagnosis of patients with atypical corneal dystrophies." (PMID 18615206, 2008). "Antibodies directed against TGFBIp were found to react to corneal deposits in TGFBI-related corneal dystrophies." (PMID 18615204, 2008). "The novel association of the mutation H626P with this atypical CDB phenotype provides further evidence of the complexities of the classification and nomenclature of the TGFBI corneal dystrophies." (PMID 18728790, 2008). "TGFBI mutations have not been associated with the mEDS spectrum of diseases but they are prevalent in corneal dystrophy, affecting the biomechanical and optical properties of the tissue." (PMID 38606288, 2024). "Targeting the TGFBI gene in organoids derived from patients with corneal dystrophy may solve the challenges of phenotypic instability in animal models, and provide a useful tool for evaluating gene editing ex vivo." (PMID 38961590, 2024). "The distribution of expressivity of TGFBI corneal dystrophies in Singaporeans, a multi-ethnic population comprising Chinese, Indian, Malaysian and others, might reflect these differences." (PMID 33513810, 2021). "Allelic homogeneity is the main factor leading to TGFBI-related corneal dystrophy." (PMID 33816482, 2021). "The majority of epithelial and epithelial–stromal TGFBI corneal dystrophies are autosomal dominant, but the patient could have been the first affected member of the family." (PMID 34301210, 2021). "Disturbance of genotype/phenotype correlation in some cases may suggest that the scheme for nomenclature and classification of the TGFBI corneal dystrophies is still imperfect, indicating that development of a modified classification system." (PMID 33513810, 2021). "TGFBI, a major causative gene for corneal dystrophies, was not clearly identified as associated with RP." (PMID 33946315, 2021). "Therefore, it is imperative to develop physiologically relevant animal models to decipher the mechanisms driving TGFBI corneal dystrophy." (PMID 32029872, 2020). "Clarifying the structure, function, and regulatory processes of the TGFBI gene and protein and understanding the genetic architecture of different corneal dystrophies and at what stages the molecular mechanisms are disrupted will determine future treatment strategies." (PMID 32366062, 2020). "Collectively, our results suggest that genome editing of TGFBI in LESCs by CRISPR/Cas9 may be useful strategy to treat corneal dystrophy." (PMID 30753226, 2019). "Collectively, our results suggest that CRISPR/Cas9 genome editing targeting the TGFBI gene in human ABCG2+/ABCB5+ double-positive LESCs may be applied therapeutically in corneal dystrophy patients." (PMID 30753226, 2019). "Our results suggest that genome editing of TGFBI in human LESCs by CRISPR/Cas9 may be useful strategy to treat corneal dystrophy." (PMID 30753226, 2019). "In addition, we used TGFBI corneal dystrophies as a model of autosomal dominant disease to assess the use of CRISPR/Cas9 in two allele-specific systems, comparing cleavage using a SNP-derived PAM to a guide specific approach." (PMID 29170458, 2017).
corneal dystrophies (continued). "To date, the majority of the literature pertaining to TGFBI has focused on corneal dystrophy." (PMID 28750100, 2017). "Mutations in the transforming growth factor beta-induced (TGFBI) gene (OMIM 601692), have been identified in several autosomal dominant (AD) corneal dystrophies, including: granular, lattice (excluding type II), Avellino, Bowman layer type I and II, and basement membrane." (PMID 22876129, 2012). "Although genetic studies on TGFBI-linked corneal dystrophies have been reported in several populations, no large genetic studies have been reported in the Taiwanese population." (PMID 22355247, 2012). "Sequencing of TGFBI can aid in the precise classification of these corneal dystrophies." (PMID 22355247, 2012). "Although a good correlation has been observed between genotype and phenotype—R555W in GCD1, R124C in LCD1, R124H in GCD2, R124L in RBCD, and R555Q in TBCD—some families having corneal dystrophies with TGFBI mutations have been reported to have variant phenotypes." (PMID 22355247, 2012). "Genetic screening of TGFBI might facilitate precise clinical diagnosis and corneal dystrophy classification, especially in patients with atypical presentation." (PMID 22355247, 2012). "Our work supports the hypothesis that corneal dystrophies with the common genetic basis of TGFBI should be grouped together as TGFBI corneal dystrophies." (PMID 21311742, 2011). "The most powerful evidence has come from TGFBI-related corneal dystrophies." (PMID 22194646, 2011). "Our work supports the hypothesis that corneal dystrophies with the common genetic basis in TGFBI should be grouped together as TGFBI corneal dystrophies." (PMID 21311742, 2011). "This suggests that in contrast to TGFBI (transforming growth factor, beta induced) with its hot spots for corneal dystrophy-associated amino acid substitution, CHST6 does not demonstrate a highly conserved number of disease-causing mutations." (PMID 19223992, 2009). "Particular mutations in TGFBI are frequently linked to special corneal dystrophy, but a genotype-phenotype correlation is not always certain." (PMID 18636123, 2008). "In addition, the results of the present study suggest that the different types of corneal dystrophy-associated TGFBI gene mutations exhibit no obvious regional or racial specificities." (PMID 30805211, 2019). "Consequently, a guide-specific treatment strategy is not suitable for targeting the mutant alleles which cause TGFBI corneal dystrophies, as an almost perfect off-target site exists in the form of the wild-type allele." (PMID 29170458, 2017). "This has however not been studied in TGFBI-associated corneal dystrophies." (PMID 27030015, 2016). "Transforming growth factor beta-induced (previously called big-H3) is related to periostin and was, in one study, reported to inhibit the mineralization of periodontal ligament cells in vitro, but later work has focused on its role in corneal dystrophy and in tumor biology." (PMID 23931052, 2013). "Transforming growth factor-beta-induced protein (TGFBI, also known as βig-H3 and keratoepithelin) is an extracellular matrix protein that plays a role in a wide range of physiological and pathological conditions including diabetes, corneal dystrophy and tumorigenesis." (PMID 22949874, 2012). "Although the mechanism underlying TGFBI-related corneal dystrophies is still unclear, we suspect that corneal dystrophy–related mutations are more likely to disrupt the interaction of TGFBI with critical binding proteins rather than altering the entire protein structure." (PMID 22605926, 2012). "In conclusion, this study highlights how phenotype-genotype correlations in TGFBI CDs may be particularly complex, making the availability of combined histopathological and genetic data necessary for the better classification of these corneal dystrophies." (PMID 21617751, 2011).
corneal dystrophies (continued). "Although molecular studies in differential diagnosis of TGFBI dystrophies have been used increasingly in clinical practice during recent years, phenotype analysis and histopathologic examination remain the “gold standard” for determining the type of corneal dystrophy." (PMID 21921985, 2011). "Uncovering the mechanism may lead to a way to inhibit the occurrence of the corneal dystrophy caused by R124H mutation in TGFBI, irrespective of the homozygous and heterozygous mutation." (PMID 19145249, 2009). "Uncovering the mechanism may facilitate us to inhibit the occurrence of the corneal dystrophy caused by the R124H mutation in TGFBI, irrespective of the homozygous and heterozygous mutation." (PMID 19145249, 2009). "There have been no other reports of the P551Q mutation of TGFBI, so it is not clear whether a heterozygous P551Q mutation causes corneal dystrophy." (PMID 19461933, 2009). "However, no case of a double mutation of TGFBI causing an autosomal dominant form of corneal dystrophy has previously been reported." (PMID 19461933, 2009). "With regard to the genetics of primary corneal dystrophies, KE is coded by the gene BIGH3, which is part of the transforming growth factor β-induced (TGFBI) gene on chromosome 5q31." (PMID 34206500, 2021). "Hence, we recommend that patients with GCD2 or any other TGFBI-linked corneal dystrophies should not be considered for LASIK surgery because the corneal opacities in the interface might increase, and the vision may worsen after the operation." (PMID 22355247, 2012). "Mutations in TGFBI have often been identified in several different stromal/Bowman’s layer corneal dystrophies, including in GCD1, GCD2, RBCD (CDB1), TBCD (CDB2), LCD1, and atypical LCDs." (PMID 22355247, 2012). "In 1994, a gene for several corneal dystrophies and the transforming growth factor-induced gene (TGFBI, also known as BIGH3) were mapped to human chromosome 5 (5q31)." (PMID 18470323, 2008). "In TGFBI-R124C mice, hyaline appeared as an unstructured amorphous deposit, unlike the hyaline observed in human TGFBI corneal dystrophy." (PMID 32029872, 2020). "Other candidates genes include transforming growth factor beta-induced (TGFBI) or zinc-finger E-box binding homeobox 1 (ZEB1), involved in corneal dystrophies or COL4A1, COL4A2, COL4A2, and COL4A1, encoding collagen proteins responsible for the proper function of the cornea." (PMID 32879808, 2020). "This information argues in favor of amyloid formation for mutations affecting leucine 509 residue, and we think that patients with p.Leu509Arg mutation of TGFBI should not be classified as EBMD, but rather as having a lattice form of corneal dystrophy." (PMID 21617751, 2011). "This atypical corneal dystrophy in a Chinese six-generation family which was identified using molecular genetic studies, is proposed as a new phenotype of CDGG1, and confirms the relationship between CDGG1 and p.R555W in the TGFBI gene." (PMID 21264234, 2011). "Despite many studies on TGFBI/BIGH3 in the development of human corneal dystrophy, its physiologic role is not yet entirely understood." (PMID 18568131, 2008). "This study aimed to clarify the role Transforming Growth Factor Beta Induced (TGFBI) protein plays in corneal epithelial homeostasis by using RNA interference and to explore the possibility of gene therapy as a treatment modality for the visually debilitating TGFBI Corneal Dystrophies (CDs)." (PMID 40665122, 2025). "The International Committee for the Classification of Corneal Dystrophies (IC3D), in its latest classification in 2015, classified corneal dystrophies into four groups: epithelial and subepithelial dystrophies, epithelial-stromal TGFBI dystrophies, stromal dystrophies, and endothelial dystrophies." (PMID 36977302, 2023).
corneal dystrophies (continued). "Despite ubiquitous expression of the keratoepithelin (KE) protein encoded by the transforming growth factor beta induced/beta induced gene human clone 3 (TGFBI/BIGH3) gene, corneal dystrophies are restricted to the cornea, and no other tissues are affected." (PMID 18568131, 2008).
ovarian carcinoma (50 papers, 2008 to 2025). A malignant neoplasm originating from the surface ovarian epithelium. "Transforming Growth Factor Beta-Induced Protein (TGFBI) expression is elevated in platelet-treated ovarian cancer cells and is associated with poorer patient outcomes." (PMID 41465326, 2025). "Hypermethylation of gene promoters, such as TGFBI, has been associated with paclitaxel resistance in ovarian cancer, suggesting that methylation status can influence drug sensitivity by altering gene expression." (PMID 41219748, 2025). "We, for the first time, proposed that high TGFBI expression was associated with poor prognosis in ovarian cancer according to our bioinformatics data and IHC staining experiments." (PMID 38395907, 2024). "IHC staining was used to analyze the expression of TGFBI encoded protein (TGFBIp) in a cohort of individuals with ovarian cancer." (PMID 38395907, 2024). "Another protein upregulated in native mouse ovaries with age, TGFBI, regulates pulmonary fibrosis and is secreted by ovarian cancer tumor-associated macrophages, promoting cancer cell migration." (PMID 37899138, 2023). "The expression levels of nc886 and TGFBI were elevated together by TGF-β in an ovarian cancer cell line and were positively associated in ovarian cancer patient samples." (PMID 37239877, 2023). "In ovarian cancer, secreted TGFBI from tumor-associated macrophages in the ascites of ovarian cancer patients have been shown to promote migration of tumor cells." (PMID 36463238, 2022). "Loss of TGFBI induced specific resistance to paclitaxel in ovarian cancer cells, and paclitaxel-resistant cells treated with recombinant TGFBI protein show restoration of paclitaxel sensitivity." (PMID 33912443, 2021). "The loss or downregulation of TGFbi (a tumor suppressor) is related to lung cancer, breast cancer, and ovarian cancers, whereas overexpression (a tumor promoter) is associated with pancreatic, colorectal, and other gastrointestinal malignancies." (PMID 32887289, 2020). "Transforming growth factor-beta-inducible gene h3 (TGFBI) hypermethylation has been shown to be associated with paclitaxel-resistance in ovarian cancer and was correlated with the loss of TGFBI mRNA expression." (PMID 28969068, 2017). "Our results show that TGFBI is frequently methylated and associated with paclitaxel-resistance in ovarian cancer." (PMID 22248469, 2012). "We compared the TGFBI mRNA expression results of these ovarian cancer tissues with the TGFBI methylation data and found a significant correlation between TGFBI methylation and loss of TGFBI mRNA expression (P < 0.001)." (PMID 22248469, 2012). "Recent findings have suggested that TGFBI also sensitizes ovarian cancer cells to paclitaxel by inducing microtubule stabilization and that the loss of TGFBI induces drug resistance and mitotic spindle abnormalities in ovarian cancer cells." (PMID 22695319, 2012). "The expression of TGFBI in clinical samples was assessed by immunehistochemical staining (IHC), and the association of TGFBI levels with the clinic-pathological characteristics and prognosis in ovarian cancer patients was evaluated by univariate and multivariate analysis." (PMID 38395907, 2024). "Apart from confirming the association between of high levels of TGFBI and poor prognosis, Steitz and colleagues found that ovarian cancer cell migration was stimulated by soluble mediators produced by macrophages from HGSOC ascites as well as IL10-stimulated monocyte-derived macrophages." (PMID 34561272, 2021). "In summary, both ISH of human tissues and gene expression data suggest a strong association of TGFBI expression and macrophages in ovarian cancer; this correlation is present in the very early stages of the disease in the FB but also in HGSOC cancers in the ovary." (PMID 34561272, 2021). "TGFBI methylation was associated with paclitaxel chemoresistance, and it can be used as a potential epigenetic biomarker and therapeutic target of paclitaxel resistance in ovarian cancer." (PMID 22248469, 2012).